CYP1B1 (cytochrome P450 family 1 subfamily B member 1)
Description:
A cytochrome P450 monooxygenase involved in the metabolism of various endogenous substrates, including fatty acids, steroid hormones and vitamins. Mechanistically, uses molecular oxygen inserting one oxygen atom into a substrate, and reducing the second into a water molecule, with two electrons provided by NADPH via cytochrome P450 reductase (NADPH--hemoprotein reductase). Exhibits catalytic activity for the formation of hydroxyestrogens from estrone (E1) and 17beta-estradiol (E2), namely 2- and 4-hydroxy E1 and E2. Displays a predominant hydroxylase activity toward E2 at the C-4 position. Metabolizes testosterone and progesterone to B or D ring hydroxylated metabolites. May act as a major enzyme for all-trans retinoic acid biosynthesis in extrahepatic tissues. Catalyzes two successive oxidative transformation of all-trans retinol to all-trans retinal and then to the active form all-trans retinoic acid. Catalyzes the epoxidation of double bonds of certain PUFA. Converts arachidonic acid toward epoxyeicosatrienoic acid (EpETrE) regioisomers, 8,9-, 11,12-, and 14,15-EpETrE, that function as lipid mediators in the vascular system. Additionally, displays dehydratase activity toward oxygenated eicosanoids hydroperoxyeicosatetraenoates (HpETEs). This activity is independent of cytochrome P450 reductase, NADPH, and O2. Also involved in the oxidative metabolism of xenobiotics, particularly converting polycyclic aromatic hydrocarbons and heterocyclic aryl amines procarcinogens to DNA-damaging products. Plays an important role in retinal vascular development. Under hyperoxic O2 conditions, promotes retinal angiogenesis and capillary morphogenesis, likely by metabolizing the oxygenated products generated during the oxidative stress. Also, contributes to oxidative homeostasis and ultrastructural organization and function of trabecular meshwork tissue through modulation of POSTN expression (By similarity).
Synonyms: CP1B; ASGD6; CYPIB1; GLC3A; P4501B1
Tractability: Small molecule: a structure with a bound ligand is known; a high-quality ligand is known; it has a binding pocket of medium quality; it belongs to a druggable protein family. Antibody: UniProt places it where antibodies can reach, with medium confidence. PROTAC: it is named in the literature on targeted protein degradation; ubiquitination databases record sites on it; a small molecule that binds it is known.
Target class: Cytochrome P450; Cytochrome P450 1B1; Cytochrome P450 family 1; Cytochrome P450 family 1B; Enzyme
Chemical probes: DMU2105, TMS
Safety:
Unwanted effects reported when the protein is acted on. In parentheses: how it was acted on, where the effect was seen, and who reports it.
chance of sensory neuropathy (source: ClinPGx)
nausea (source: ClinPGx)
Gene: Protein-coding gene on chromosome 2 (38,066,973 to 38,109,902, reverse strand). Ensembl gene ENSG00000138061.
Subcellular location: Endoplasmic reticulum membrane; Microsome membrane; Mitochondrion
Subcellular location (Human Protein Atlas): Mitochondria
Pathways (Reactome):
Metabolism: Endogenous sterols; Synthesis of (16-20)-hydroxyeicosatetraenoic acids (HETE); Synthesis of epoxy (EET) and dihydroxyeicosatrienoic acids (DHET)
Disease: Defective CYP1B1 causes Glaucoma
Gene Ontology:
Molecular function: estrogen 16-alpha-hydroxylase activity; estrogen 2-hydroxylase activity; heme binding; monooxygenase activity; oxidoreductase activity, acting on paired donors, with incorporation or reduction of molecular oxygen, reduced flavin or flavoprotein as one donor, and incorporation of one atom of oxygen; protein binding; testosterone 6-beta-hydroxylase activity; oxidoreductase activity, acting on paired donors, with incorporation or reduction of molecular oxygen, NAD(P)H as one donor, and incorporation of one atom of oxygen; steroid hydroxylase activity; arachidonate 11,12-epoxygenase activity; arachidonate 14,15-epoxygenase activity; arachidonate 8,9-epoxygenase activity; hydroperoxy icosatetraenoate dehydratase activity; iron ion binding; oxidoreductase activity, acting on paired donors, with incorporation or reduction of molecular oxygen
Biological process: arachidonate metabolic process; estrogen metabolic process; retinal metabolic process; retinol metabolic process; steroid metabolic process; xenobiotic metabolic process; blood vessel morphogenesis; cell adhesion; cellular response to hydrogen peroxide; collagen fibril organization; endothelial cell migration; epoxygenase P450 pathway; intrinsic apoptotic signaling pathway in response to oxidative stress; lipid catabolic process; negative regulation of cell adhesion mediated by integrin; negative regulation of cell migration; negative regulation of cell population proliferation; nitric oxide biosynthetic process; omega-hydroxylase P450 pathway; positive regulation of angiogenesis; positive regulation of apoptotic process; positive regulation of receptor signaling pathway via JAK-STAT; positive regulation of vascular endothelial growth factor production; regulation of reactive oxygen species metabolic process; retinal blood vessel morphogenesis; and 8 more
Cellular component: endoplasmic reticulum membrane; mitochondrion
Genetic constraint (gnomAD): Loss-of-function variants: 22 observed, 28.83 expected, observed/expected ratio (o/e) 0.76, 90% interval 0.54 to 1.09. The synonymous counts are far from expectation, so gnomAD's model fits this gene poorly and the ratio says little. Missense variants: 883 observed, 728.48 expected, observed/expected ratio (o/e) 1.21, 90% interval 1.15 to 1.28. Synonymous variants: 375 observed, 305.47 expected, observed/expected ratio (o/e) 1.23, 90% interval 1.13 to 1.34.
Gene-disease validity (ClinGen):
ClinGen rates the evidence that CYP1B1 causes each of these diseases.
CYP1B1-related glaucoma with or without anterior segment dysgenesis (autosomal recessive): Definitive. Any primary congenital glaucoma in which the cause of the disease is a mutation in the CYP1B1 gene.
Homologues: Orthologues: chimpanzee CYP1B1 (98% identical), macaque CYP1B1 (94% identical), pig CYP1B1 (85% identical), dog CYP1B1 (84% identical), rabbit CYP1B1 (84% identical), mouse Cyp1b1 (81% identical), guinea pig CYP1B1 (81% identical), rat Cyp1b1 (80% identical), tropical clawed frog cyp1b1 (55% identical), zebrafish cyp1b1 (53% identical). Paralogues in human: CYP1A1 (36% identical), CYP1A2 (35% identical).
Diseases named in the same sentence as CYP1B1 in open-access papers:
CYP1B1 is named in the same sentence as 239 diseases in open-access papers, as found by Europe PMC text mining. Sharing a sentence is not in itself a finding about the gene and the disease. The quoted sentences say what the papers report.
breast carcinoma (137 papers, 2003 to 2025). "CYP1B1 polymorphisms have been shown to modulate estrogen regulatory enzyme activity, promoting the occurrence of breast cancer." (PMID 40989158, 2025). "A studyon breast cancer showed that, there was an association of CYP1B1*3-polymorphisms with microsites reactions in response to paclitaxelbased chemotherapy." (PMID 40092865, 2024). "Both mRNA and protein levels of CYP1B1 are elevated with BOLD-100 treatment in MCF7 breast cancer cells; notably, CYP1B1 induction is associated with chemotherapy resistance." (PMID 38672458, 2024). "On the other hand, authors from Iran found the association between CYP19A1 (rs749292) (also for CYP2C8 (rs1058930), CYP1B1 (rs1056836)) genes’ polymorphisms and increased risk of breast cancer in women in Mazandaran province." (PMID 35160095, 2022). "Analysis of clinical breast cancer tumor samples revealed an association between tumors exhibiting higher CYP1B1 RNA levels and diminished overall and disease-free survival." (PMID 36077068, 2022). "HA, combined with polyethyleneimine in nano form, was loaded with docetaxel and α-napthtoflavone (an inhibitor of CYP1B1) to overcome the MDR caused by CYP1B1 in breast cancer cells." (PMID 35645591, 2022). "Compared with the wild-type genotypes of CYP1B1 rs1056827 (CC), the homozygous variant genotypes (AA) showed a significantly higher risk in breast cancer, yielding an OR of 6.90 (95% CI = 1.50–31.76)." (PMID 33632172, 2021). "Compared with the wild-type genotypes of CYP1B1 rs1056836 (GG), the heterozygous variant genotypes significantly reduced the risk of breast cancer, yielding an OR of 0.37 (95% CI = 0.21–0.67)." (PMID 33632172, 2021). "In this study, we found that the variant allele of CYP1B1 rs1086836 was involved in reducing the risk of breast cancer and that the exact mechanism of the protection of this variant allele was not clear." (PMID 33632172, 2021). "In a case–control study, the carriers of the CYP1B1*3 allele were significantly more frequent among breast cancer women, than those in the controls." (PMID 34462889, 2021). "It was already shown that polymorphisms in CYP1B1 can influence its activity and thus are associated with cancer, namely breast cancer." (PMID 35582590, 2019). "The group of Boso reported that CYP1B1*3 is associated with stomatitis and mucositis in paclitaxel-treated breast cancer patients." (PMID 29507678, 2018). "E2 and the resulting hydroxylated metabolites from cytochrome P450s CYP1A1 and CYP1B1 have been implicated in breast cancer." (PMID 28212313, 2017). "For example, evidences demonstrated that CYP1B1 is regulated by miR-27b, and a decreased miR-27b expression is inversely associated with an increased protein level of CYP1B1 in breast cancer patients." (PMID 25704921, 2015). "In a case-control study of American postmenopausal women (PACE), the authors found an association between CYP1B1; rs1056827 and breast cancer risk in ever EPT users." (PMID 23095343, 2012). "Presence of wild-type CYP1B1 was reported to be associated with protection against breast cancer in a population of Indian women." (PMID 21510869, 2011). "To evaluate this in a rural Ningxia Han population of P. R. China, we analysed the association between CYP1B1 codon 119 (Ala→Ser) and codon 432 (Val→Leu) and risk of breast cancer." (PMID 20212917, 2010). "Studies investigating possible associations between cytochrome P4501B1 (CYP1B1) polymorphisms and breast cancer risk have been inconsistent." (PMID 20212917, 2010). "Further investigations involving larger sample sizes and other ethnic populations are needed in order to establish more completely the relationship between these CYP1B1 SNPs and breast cancer risk." (PMID 20212917, 2010). "Previous studies on the association between CYP1B1 codon 119(G→T) and codon 432(G→C) and breast cancer in different populations have often given rise to conflicting or contradicting results." (PMID 20212917, 2010).
breast carcinoma (continued). "Our results suggest that the codon 432 polymorphism of the CYP1B1 gene is associated with increased risk of breast cancer and is particularly involved in breast cancer risk in premenopausal women of African descent." (PMID 19208203, 2009). "This study has demonstrated a role for the CYP1B1 Val → Leu polymorphism in premenopausal breast cancer risk in Nigerian women." (PMID 19208203, 2009). "Statistical significance for the association between breast cancer and the CYP1B1 Val/Val polymorphism was reached in two studies." (PMID 19208203, 2009). "The heterozygous CYP1B1 (Val/Leu) genotype was associated with a significant increased risk of breast cancer (Odds ratio [OR] = 1.59, 95% Confidence Interval [CI] 1.01–2.52), compared with the homozygous wild type CYP1B1 (Val/Val) genotype." (PMID 19208203, 2009). "Several molecular epidemiological studies have evaluated the association of polymorphisms in CYP1B1 gene and breast cancer risk in various populations, including seven in Caucasian and four in Asian populations." (PMID 19208203, 2009). "The distribution of the CYP1B1 (Val) and CYP1B1 (Leu) alleles in postmenopausal breast cancer cases and controls were similar." (PMID 19208203, 2009). "Our results suggest that harboring one CYP1B1 (Leu) allele was significantly associated with breast cancer (OR = 1.59, 95% CI 1.01–2.52)." (PMID 19208203, 2009). "In premenopausal women, harboring at least one CYP1B1 (Leu) allele conferred a significant two-fold increased risk of breast cancer (OR = 2.04, 95% CI 1.10–3.78)." (PMID 19208203, 2009). "The risk of premenopausal breast cancer with the heterozygous CYP1B1 (Val/Leu) and homozygous CYP1B1 (Leu/Leu) genotypes combined was 2.04 (95% CI 1.10–3.78)." (PMID 19208203, 2009). "The risk of premenopausal breast cancer associated with the CYP1B1 genotypes remained essentially unchanged when WHR was included in the model." (PMID 19208203, 2009). "Several other investigators have evaluated the relationship between CYP1B1 polymorphisms and breast cancer in different populations." (PMID 19208203, 2009). "A case-only study on breast cancer also reported that the combination of cigarette smoking and CYP1B1 1294G allele was associated with a higher risk of breast cancer." (PMID 17603900, 2007). "In a recent breast cancer case -control study, including categorical values only (genotypes), a four-locus susceptibility model including the polymorphisms of COMT, CYP1A1m1, CYP1B1 codon 48, and CYP1B1 codon 432 was found associated with breast cancer." (PMID 16412218, 2006). "In this population-based cohort of women with BBD, there was evidence of an increased risk of breast cancer among women who carried the CYP1B1 453Ser allele compared to women who carried two copies of the CYP1B1 453Asn allele." (PMID 16808847, 2006). "A case–control study was performed to assess the potential influence of CYP19 Arg264Cys and CYP1B1 Leu432Val polymorphisms on breast cancer risk in a series of Korean breast cancer patients and controls." (PMID 12618873, 2003). "In this study, we have evaluated the potential influence of CYP19 Arg264Cys and CYP1B1 Leu432Val polymorphisms on the breast cancer risk among Korean women as an extension of our previous work in this study population." (PMID 12618873, 2003). "Additionally, CYP1B1 also increased the risk for breast cancer through promoting the production of reactive quinones that lead to DNA damage." (PMID 41212877, 2025). "CYP1B1 polymorphisms have also been found to increase the risk of prostate and breast cancer." (PMID 37762649, 2023). "However, BMI was the only breast cancer risk factor influencing fluxes to adducts of estrogens with DNA, probably by increasing levels of CYP1B1 and/or decreasing those of SULT1A2 in addition to increasing estrogen levels." (PMID 34921608, 2022).
breast carcinoma (continued). "CYP1B1 is involved in the metabolism of sterols, and its increased activity is associated with the occurrence of various types of cancer, including prostate, uterus and breast cancers." (PMID 35008866, 2021). "In addition, human breast cancer-associated fibroblasts upregulate the canonical AhR target gene, CYP1B1, and proliferate in response to treatment with the AhR ligand, 3-methylcholanthrene." (PMID 33763068, 2021). "Moreover, a higher expression of CYP1B1 was observed to be associated with increased drug resistance in breast cancer cells corroborating its role as a predictor of drug resistance and a prognostic indicator of treatment." (PMID 33809117, 2021). "The high adduct ratios in women at high risk for breast cancer and the association of SNPs in CYP1B1 and COMT with increased odds of ovarian cancer provide particularly strong evidence for a critical role of estrogen-DNA adducts in the etiology of these cancers." (PMID 30854528, 2017). "Although it is controversial, one of the CYP1B1 polymorphic variants, Leu432Val, which may increase enzymatic activity, is associated with low response to taxane in breast cancer and poor prognosis in docetaxel-treated prostate cancer patients." (PMID 25860934, 2015). "For example, high soy isoflavone intake may reduce the risk of breast cancer caused by CYP1B1 risk genotypes." (PMID 26114387, 2015). "CYP1B1 belongs to the cytochrome P450 super family of enzymes and is important in the metabolism of estrogen that may affect breast cancer risk." (PMID 23095343, 2012). "Those SNPs located in ERα, ERβ, HSD17B1, COMT and CYP1B1 genes may also be associated to mammographic density (MD), which is a strong and independent risk factor for breast cancer." (PMID 21092186, 2010). "The mechanisms through which polymorphisms in CYP1B1 might influence breast cancer risk are not completely known." (PMID 19208203, 2009). "Given the carcinogenic and estrogenic potential of 4-OH-E2, it is plausible to speculate that inheritance of the CYP1B1 432Leu allele may contribute to increased breast cancer risk associated with estrogen-mediated carcinogenesis." (PMID 19208203, 2009). "However, such an interaction if present in our study population would result in underestimation of the breast cancer risk associated with the presence of the CYP1B1 (Leu) allele." (PMID 19208203, 2009). "Moreover, CYP1B1 polymorphisms are known predisposing factors in male patients with breast cancer." (PMID 40989158, 2025). "In recent years, several studies have reported that CYP1B1 G119T polymorphic status might be associated with hereditary predisposition in Asian individuals, particularly when it comes to breast cancer and prostate carcinoma, suggesting the potential roles of CYP1B1 in tumor progression." (PMID 35003394, 2021). "Consequently, interactions between E2 exposures during key life stages as modeled here and the E2-regulating genes Cyp1b1 and Comt may modify breast cancer risk." (PMID 20435547, 2010). "Our research performed on MCF7 and MDA-MB-231 breast cancer cell lines has shown that resveratrol inhibited the expression of CYP1B1." (PMID 40807256, 2025). "In vitro studies then confirmed that antioxidants led to AhR activation with increased CYP1B1 levels in two breast cancer cell lines." (PMID 40646277, 2025). "Tangeretin was subsequently shown to induce CYP1 activity and CYP1A1/CYP1B1 expression in MCF7 and MDA-MB-468 cells, suggesting that this flavone inhibits the proliferation of breast cancer cells via CYP1A1/CYP1B1-mediated metabolism to 4′-hydroxy tangeretin." (PMID 40807256, 2025). "Other malignancies, such as lung, prostate, bladder, ovarian, colorectal, and breast cancers, have also been shown to overexpress CYP1B1." (PMID 41155673, 2025). "CYP1B1 encodes a member of the cytochrome P450 superfamily of enzymes and can be induced by COX-2 in human breast cancer cells." (PMID 41293174, 2025).